MEIOSIN (meiosis initiator)
Description:
Gatekeeper of meiotic initiation in both male and female germ cells. In complex with STRA8, directly activates the transcription of a subset of critical meiotic genes playing a central role in cell-cycle switching from mitosis to meiosis. Temporal expression of MEIOSIN is required for meiotic entry decision.
Synonyms: BHMG1; HMGDC
Tractability: No criterion of Open Targets' tractability assessment is met for any kind of drug.
Gene: Protein-coding gene on chromosome 19 (45,733,439 to 45,764,541, forward strand). Ensembl gene ENSG00000237452.
Subcellular location: Nucleus
Subcellular location (Human Protein Atlas): Nucleoplasm
Gene Ontology:
Molecular function: protein dimerization activity
Biological process: activation of meiosis; cellular response to retinoic acid; meiotic cell cycle; oogenesis; regulation of transcription by RNA polymerase II; spermatogenesis
Cellular component: nucleus
Homologues: Orthologues: chimpanzee MEIOSIN (99% identical), macaque MEIOSIN (95% identical), dog MEIOSIN (65% identical), pig MEIOSIN (54% identical), guinea pig MEIOSIN (50% identical), rat Meiosin (48% identical), mouse Meiosin (47% identical), zebrafish meiosin (13% identical).
Diseases named in the same sentence as MEIOSIN in open-access papers:
MEIOSIN is named in the same sentence as 3 diseases in open-access papers, as found by Europe PMC text mining. Sharing a sentence is not in itself a finding about the gene and the disease. The quoted sentences say what the papers report.
ovarian disease (1 paper, 2023). "Although STRA8 and MEIOSIN are well known for their roles in initiating meiosis in animal models, our findings highlight their critical roles in human ovarian disease." (PMID 36732629, 2023).
MEIOSIN also shares sentences with these, for which no sentence is quoted: asthma (1 paper); cancer (1).